CCL2 (C-C motif chemokine ligand 2)
Diseases named in the same sentence as CCL2 in open-access papers (continued):
Sharing a sentence is not in itself a finding about the gene and the disease.
cancer (continued). "Another cancer cell-derived factor that could be potentially involved in the polarization of MAMs in our model is CCL2 (~10-fold higher expression in parenchymal versus dural 4T1 cancer cell variants), which has been previously implicated in the M2 activation of human macrophages." (PMID 27203741, 2016). "When cancer cells were cocultured with ADSCs in which CCL2‐induced lipolysis had been inhibited, their migration was significantly reduced compared to coculture with control ADSCs." (PMID 41160815, 2026). "Our earlier findings indicate that increased FA supply activates the FA/HIF‐1α/CCL2 axis in cancer cells." (PMID 41160815, 2026). "In summary, our study establishes a critical interplay between two axes: the FA–HIF‐1α–CCL2 axis in cancer and the CCL2–PPARα–FA axis in adipose tissue." (PMID 41160815, 2026). "This indicates that the presence of lipids from ADSCs boosts CCL2 expression and its secretion from cancer cells into the coculture‐derived CM." (PMID 41160815, 2026). "Cancer cells drive adjacent adipose tissue to release fatty acids by secreting CCL2, which activates PPARα‐dependent lipolysis." (PMID 41160815, 2026). "Our results demonstrate that cancer‐derived CCL2 acts as a signaling molecule that regulates lipid metabolism in adipose tissues through the CCL2/CCR2/PPARα pathway." (PMID 41160815, 2026). "This evidence strongly indicates that the FA‐HIF‐1α‐CCL2 axis in cancer plays a pivotal role in activating CCR2‐mediated signaling within the adjacent adipose tissue under obese condition." (PMID 41160815, 2026). "We compared CCL2 mRNA levels in the sorted cancer cells grown in coculture with ADSCs versus those in monoculture." (PMID 41160815, 2026). "To examine the impact of cancer cell‐derived CCL2 on adipose tissue, we conducted gene ontology analysis." (PMID 41160815, 2026). "C‐C motif chemokine ligand 2 (CCL2) is a nerve‐secreted chemokine that mediates the neural invasion of CCR2‐positive cancer cells." (PMID 41556039, 2026). "Our comprehensive analysis of cytokine arrays and cocultured cancer cells revealed a significant increase in CCL2 driven by ADSC‐derived FAs among the target cytokines of HIF‐1α." (PMID 41160815, 2026). "To see if blocking the crosstalk between adipose tissue and tumors with a neutralizing antibody against CCL2 can suppress cancer progression, we conducted in vivo experiments and analyzed key genes and proteins involved in their interaction." (PMID 41160815, 2026). "Activation of HIF‐1α induced by FA influx increases CCL2 expression in cancer cells, which subsequently leads to lipolysis in nearby adipose tissue by activating peroxisome proliferator‐activated receptor alpha (PPARα) signaling." (PMID 41160815, 2026). "CCL2 and CSF2 were predominantly distributed in Mono-Macro cells, and cancer-associated fibroblast (CAF) showed sporadic expression." (PMID 40535567, 2025). "For instance, in response to cancer cell conditioned media, CAFs upregulate expression of chemokines such as CCL2, which, together with CCL3 and CCL4 can recruit myeloid cells to the TME." (PMID 39743376, 2025). "Previous studies have reported that S100A8/A9 increases the expression levels of IL-1β and CCL2 through p38 MAPK/JNK/AP-1 signaling in cancer cells 17-21." (PMID 40860162, 2025). "CCL2 has a proven role in drug resistance by activating the PI3K-Akt-mTOR signaling pathway in different cancers: breast, gastric, glioma, lung, and ovarian." (PMID 40076892, 2025). "Similar to the mouse cell lines, PLX51107 treatment of human cancer cell lines resulted in reduced protein levels of CCL2 and CXCL5 (P < 0.01)." (PMID 40762981, 2025). "Specifically, sPD-L1 inhibited T lymphocyte activation, while CCL2 recruited monocytes, dendritic cells (DCs), and other cells to the site of inflammation, thereby contributing to cancer pathogenesis." (PMID 40149259, 2025). "Cancer cells secrete chemokines like CCL2/MCP-1, CCL5, and CCL8/MCP-2, which recruit TAMs into the TME." (PMID 40361472, 2025).
cancer (continued). "Both CCL2 and CCL4can be secreted by activated leukocytes, lymphocytes, endothelial and cancer cells, and are chemoattractants for natural killer cells and monocytes." (PMID 39996747, 2025). "CCR2, a critical receptor of CCL2, was initially identified as a crucial receptor for cytotoxic T cell migration towards cancer cells." (PMID 40282185, 2025). "Carlumab, an anti-CCL2 monoclonal antibody, has demonstrated promising results in preventing the development of certain cancers in mouse models." (PMID 40083710, 2025). "Another interesting modulation is the overall robust down‐regulation of CCL2 chemokine in the three endothelial cell models, in eight out nine co‐culture conditions with cancer cells or CAFs." (PMID 40348600, 2025). "Previous studies have demonstrated that genetic and pharmacologic targeting of Axl decreases expression and secretion of CCL2 in mouse cancer models." (PMID 40149328, 2025). "In the TME, CCL2 is synthesized by various cell types such as cancer cells and stromal cells in response to various stimuli." (PMID 41341593, 2025). "Numerous studies have demonstrated that cancer cells secrete a variety of chemokines and cytokines, including IL-10, CCL2, CCL18, and CXCL4, to recruit TAMs and establish an immunosuppressive microenvironment." (PMID 39972459, 2025). "Since IL-6 and CCL2 are representative markers of inflammatory fibroblasts, our results indicate that cancer cell-derived DKK1 induces lung fibroblasts to adopt an inflammatory phenotype." (PMID 40025612, 2025). "We found that cancer cells, and endothelial cells expressed CCL2 or CXCL2, which recruit macrophages, explaining the dominance of myeloid cells in CNSm." (PMID 40883281, 2025). "Several reports have shown that monitoring CCL2 levels in the blood would be useful as a biomarker for predicting prognosis in cancer patients." (PMID 40343498, 2025). "Treatment with TNBC-derived EVs upregulated the expression of cancer-associated adipocyte pro-inflammatory markers, including CXCL8, CCL2, and IL-1β, in hADMSC." (PMID 40940890, 2025). "In the pre-metastatic microenvironment, CCL2 secreted by cancer cells and bone marrow cells attracts and induces M2-TAM and other cells to activate Wnt/β-catenin signaling pathway, which destroys the E-cadherin junction between early cancer cells." (PMID 41341593, 2025). "In conclusion, the interplay between these inflammatory mediators—IL-6, IL-1β, TNF-α, CCL2, PGE2, GM-CSF, and bradykinin—highlights their collective role in the mechanisms underlying cancer pain." (PMID 40579593, 2025). "In fact, some scholars have also provided some insights into the potential therapeutic benefits of using novel delivery systems targeting the CCL2/CCR2 axis to treat cancer and inflammation." (PMID 41445742, 2025). "Several studies have confirmed that overexpression of various transcription factors in cancer cells can affect the transcription process of CCL2." (PMID 41341593, 2025). "Therapeutics that specifically target the CCL2/CCR2 chemokine axis are currently in clinical trials for cancer indications." (PMID 39883518, 2025). "Twist1 up-regulation in cancer cells activates the transcription of CCL2 mRNA, thus promoting CCL2 expression." (PMID 41341593, 2025). "Consistent with this phenotype, PT-associated macrophages expressed inflammatory cytokines (TNF, IL6) and pro-tumorigenic factors (CCL2, CCL3, CCL4, CXCL16) linked to cancer progression and invasiveness." (PMID 41346635, 2025). "LYVE1-expressing macrophages have been shown to have a role in maintaining a proangiogenic perivascular niche in cancer, and CCL2 is the primary chemokine responsible for the recruitment of angiogenic macrophages." (PMID 40647416, 2025).
cancer (continued). "In vitro experiments showed that upregulation of Twist1 in cancer cells activated CCL2 mRNA transcription; A chemotactic gradient is generated by the secretion of CCL2 protein to promote macrophage infiltration and subsequent angiogenesis stimulation." (PMID 41341593, 2025). "CAFs also secrete M-CSF, IL6, IL8, HGF, and CCL2, which induce the differentiation of a specific macrophage phenotype characterized by high expression of CD163 and CCL2, leading to increased cancer cell invasion in CRC." (PMID 41213902, 2025). "Another approach is to target the cancer-cell-derived chemokine CCL2, which recruits CCR2+ inflammatory monocytes to the TME, where they become immunosuppressive MDSCs and TAMs." (PMID 40917508, 2025). "Chemokines such as CCL2, CCL5, CCL4, and CXCL8 have been implicated in the initiation and progression of cancer." (PMID 41200178, 2025). "In these noncytotoxic concentrations, either Cis or Doxo stimulated the expression of CCL2, a specific factor involved in stromal–cancer cell communication." (PMID 39061870, 2024). "WAT releases inflammatory molecules, such as IL6, TNF, and CCL2, which can contribute to cancer progression by promoting inflammation." (PMID 39011399, 2024). "The study proposed a novel mechanism through which TAM secreted CCL2 activates the PI3K/Akt pathway in cancer cells upon binding to its CCR2 receptor." (PMID 39044824, 2024). "CCL2 expression both in cancer cells and TAMs was shown to be regulated through direct binding of β-catenin to the CCL2 gene promoter." (PMID 39044824, 2024). "TAMs originate from circulating monocytes, which are summoned to neoplastic sites by an array of chemokines and growth factors, such as CCL2 and CSF-1, released by cancer cells." (PMID 39290697, 2024). "In this study, we demonstrated significantly higher levels of circulating PD-L1, CXCL10, MIG, HGF, CCL-2, and IL-6 in cancer patients compared to normal healthy subjects." (PMID 38776028, 2024). "CCL2 released by cancer cells was shown to increase macrophage migratory capacity and induce M2 polarization in vitro." (PMID 39044824, 2024). "Therapeutic agents targeting CCL2 have demonstrated therapeutic effects in preclinical cancer models." (PMID 39606239, 2024). "CCL2 has also been reported to induce resistance against immunotherapy in aggressive cancers like TNBC." (PMID 39125273, 2024). "Similar trends were observed in the 3D co-cultures with primary monocyte cells, hMSC and HCT116 cancer cell lines where there was a trend increase in CCL2, CCL5 and GM-CSF in cultures with the hMSCs." (PMID 39310770, 2024). "When TGF-β was present, Th17 cells played a pro-cancer role by secreting IL-17 and IL-22, while when IL-1βwas present, Th17 inducing CCL2 and CCL20 expression, DCs, and other immune cells were activated and recruited, resulting the inhibition of COAD." (PMID 39252305, 2024). "In recent years, the chemokine CCL2 (C-C motif ligand 2), also known as monocytic chemotactic protein 1 (MCP-1), and its receptor CCR2 (C-C motif receptor 2) have gained attention for their association with cancer occurrence and therapeutic resistance." (PMID 39199567, 2024). "The levels of circulating PD-L1, CXCL10, MIG, HGF, CCL-2, and IL-6 were significantly higher in the cancer group compared with those of the control group." (PMID 38776028, 2024). "HER2 is known to promote cancer cell proliferation and survival as well as secretion of CCL2, a chemokine that recruits monocytes and macrophages and inhibits M1-like macrophage polarization." (PMID 38918836, 2024). "CCL2 promotes progression, migration, invasion, and immune‐suppressive immune cell infiltration in cancer cells; thus, tumorigenesis and progression decrease in the presence of this phytochemical." (PMID 39055196, 2024). "There are intriguing insights into the dynamics of treating cancer patients with Carlumab to target CCL2." (PMID 39076996, 2024).
cancer (continued). "MRI‐based radiomics was used to predict CCL2 expression level using data obtained from The Cancer Imaging Archive (TCIA) and The Cancer Genome Atlas (TCGA) databases." (PMID 39030882, 2024). "This process helps explain why the overproduction of CCL2 in cancer cells correlates with enhanced metastatic potential in various cancer types." (PMID 39201480, 2024). "TNF-α induced a significant increase in the secretion of chemokines and cytokines from CT26 cancer cells including CCL2, CCL3, CCL4, CCL5 and G-CSF." (PMID 39310770, 2024). "Here, we advance the understanding of how Siglec-sialoglycan interactions on suppressive myeloid cells can shape an immunosuppressive environment via the secretion of inhibitory CCL2 in the context of cancer across different human and murine models." (PMID 38448555, 2024). "B3GNT5 is capable of suppressing the activation and proliferation of T lymphocytes by promoting the secretion of TGF-β and CCL2 by CSCs (cancer stem cells)." (PMID 39671359, 2024). "CCL2-positive cancer cells recruit macrophages that express the CCL2 receptor and, following cancer cell extravasation, promote the growth of brain metastases." (PMID 39769140, 2024). "CCL2 is extensively involved in disease regulation, particularly in inflammation, fibrosis, and cancer." (PMID 39850880, 2024). "Cancer cells release CCL2 to recruit classical monocytes expressing its receptor CCR2 for the promotion of metastasis and resistance to immunosurveillance." (PMID 39545417, 2024). "CAFs activated by cocultured BC cells produce higher levels of chemokine (C-C motif) ligand 2 (CCL2, bSE = 5.0), which stimulates the stem cell-specific, sphere-forming phenotype in BC cells and cancer stem cell (CSC) self-renewal." (PMID 39335478, 2024). "Genes such as APRT, CCL2, BEX2, MGC26963, and PLAU were identified as key genes significantly associated with cancer progression." (PMID 38970097, 2024). "There are several vital reasons why clinical trials for ABN912 (another anti-CCL2 mAb) and Carlumab, intended to treat RA and cancer, have been unsatisfactory." (PMID 39076996, 2024). "Four key genes CCL2, CCR7, LY96, and PTPRC, from ClusterK1 and five genes AURKA, CDK1, CCNA2, FEN1, and PLK1 from ClusterK2, were associated with at least one type of cancer." (PMID 38872418, 2024). "HIF‐1A and CCL2 have been shown to play a pivotal role in the recruitment of monocytes and cancer progression; however, the interrelationship between these two factors varies in solid tumor types." (PMID 35658112, 2024). "Our present results add a relevant action of CCL2 on lactate transporter protein levels and, therefore, changes in mitochondrial substrate preferences in epithelial cancer cells." (PMID 39061870, 2024). "The development of CCR2 inhibitors has brought positive results in cancer treatment, and multiple CCL2-neutralizing antibodies are being tested in clinical trials." (PMID 39003350, 2024). "Recently, CCL2 has attracted attention as a target in cancer therapy because of its immunosuppression in cancer extensions." (PMID 38529405, 2024). "Mechanistically, C-C motif chemokine ligand 2 (CCL2), produced mainly by astrocytes, promotes cancer cell chemotaxis through CCR2." (PMID 37307835, 2024). "IL-6, IL-8, and CCL2 secreted from neighboring Mφs have been shown to alter the phenotype of cancer cells." (PMID 38486225, 2024). "miR-19a-containing exosomes are secreted by astrocytes and taken up by cancer cells to promote CCL2 expression." (PMID 37307835, 2024). "A CCL2 paracrine feedback loop between macrophages and cancer cells promotes BC growth and metastasis." (PMID 39044824, 2024). "Several CC chemokines, such as CCL1, CCL2, CCL5, CCL18, and CCL21, have been implicated in cancer, exhibiting both pro- and anti-tumorigenic roles." (PMID 39409924, 2024). "According to a recent study, CCL2 was reported to be a potential predictor of neurotoxicity in cancer patients treated with ICIs." (PMID 38776028, 2024).
cancer (continued). "Cancer cells release inflammatory factors (CCL2, CXCL12, CX3CL1, GDNF, CSF-1), leading to microglia chemoattraction and eventually inducing its shift to the M2 phenotype." (PMID 38671983, 2024). "The central regulator of monocyte mobilization from the bone marrow is CCL2, which is often highly accumulated in the serum of cancer patients." (PMID 39459945, 2024). "Thus, CCL2 expression in 4T1 carcinoma cells may be associated with disease progression." (PMID 38973385, 2024). "TAMs can promote cancer cell proliferation and survival by secretion of a variety of chemokines and cytokines like IL-1α, IL-1β, TNFα, TGFβ, IL-6, IL-8, CCL2, and TEXs." (PMID 38017494, 2023). "Cancer-associated fibroblast (CAF) sub-clusters showing high expression of IL6, CCL2, S100A4, PDPN, and FGF7 were identified in both primary and metastatic samples." (PMID 38328306, 2023). "Accordingly, we found increased CCL2 protein in the supernatant of cocultured neurons and human cancer cell lines SU.86.86, T3M4, and DLD-1." (PMID 37607005, 2023). "Exposure of HNSCC to ionizing radiation has shown an increase in the expression of CCL2 by cancer cells, leading to the recruitment of CCR2 + Tregs into the tumor." (PMID 37221555, 2023). "It has been approved that the release of some chemokines such as CCL2 by cancer and stromal cells participates in the recruitment of monocytes." (PMID 37221555, 2023). "Mechanistically, in premalignant lesions, CCL2 produced by cancer cells and myeloid cells attracted CD206+/Tie2+ macrophages and induced Wnt-1 upregulation, which in turn downregulated E-cadherin junctions in HER2+ early cancer cells." (PMID 37208442, 2023). "In brief, CCL2 has been detected in both cancer cells and stromal cells, including TAMs, fibroblasts, and ECs (lymphocytes in one study)." (PMID 37208442, 2023). "CCL2 is one such chemokine and is well known for its role in recruiting immune cells; however, in many cancers, CCL2 is involved in cancer malignancy and is known to suppress the actions of immune cells." (PMID 37239133, 2023). "In our study, we screened for chemokines that were increasingly secreted from DRG neurons when confronted with cancer cells and detected increased production of CCL2." (PMID 37607005, 2023). "The aim of the current study was to examine the functions of endogenous CCL2 of MSCs in cancer biology." (PMID 36672395, 2023). "The recruitment of CCL2 during PMN formation plays critical roles in cancer metastasis target organs." (PMID 37056561, 2023). "Previous IHC studies indicated that both cancer cells and stromal cells, such as macrophages, fibroblasts, and ECs, are well-known sources of CCL2 in human BC tissues." (PMID 37208442, 2023). "Propagermanium inhibits macrophage migration by inhibiting binding between CCR2 and CCL2, thereby suppressing cancer metastasis." (PMID 36768216, 2023). "Cancer cells and the surrounding stromal cells are the sources of CCL2, and they increase the number of IMs in the peripheral blood." (PMID 36831085, 2023). "According to these documents, the CCR2_CCL2 signaling pathway plays a key role in the development of cancer, which makes the CCR2 receptor an important and potential therapeutic target in cancer treatment." (PMID 37325423, 2023). "Numerous types of research have been done to study the effect of CCR2_CCL2 signaling pathway inhibition in preventing cancer progression." (PMID 37325423, 2023). "There are only a few studies evaluating the role of cancer cell-derived CCL2 in metastasis to the bone and brain." (PMID 37208442, 2023). "In cancer bone metastasis, CCL2 signaling is activated via binding of CCL2 ligand to the CCR2 and CCR4 receptors." (PMID 37607005, 2023). "MSC-derived CCL2 contributes to cancer progression not only by attracting TAMs but also by facilitating their M2-polarization." (PMID 36672395, 2023).